GLO1 (glyoxalase I)
Diseases named in the same sentence as GLO1 in open-access papers (continued):
Sharing a sentence is not in itself a finding about the gene and the disease.
cancer (continued). "Modulating Glo1 activity is considered a potential approach to sensitize cancer cells to existing therapies or induce direct cytotoxic effects." (PMID 38785990, 2024). "Modulating GLO1 activity has emerged as a strategy to sensitize cancer cells to existing therapies or induce direct cytotoxic effects." (PMID 38785990, 2024). "The glyoxalase system, comprising GLO1 and GLO2 enzymes, is integral in detoxifying methylglyoxal (MGO) generated during glycolysis, with dysregulation implicated in various cancer types." (PMID 38785990, 2024). "In conclusion, MG and Glo1 play pivotal roles in cancer biology, influencing cell proliferation, survival, and apoptosis." (PMID 38398772, 2024). "Altered expression levels of GLO1 have been reported in various cancer types, with increased expression potentially serving as an adaptive response to counteract MGO-induced damage." (PMID 38785990, 2024). "Altered GLO1 expression in cancer showcases its complex role in cellular adaptation and cancer aggressiveness." (PMID 38785990, 2024). "Glo-1 inhibition depresses cell proliferation and induces apoptosis in cancer cells, the degree of which is dependent on the concentration of generated MEG." (PMID 38187538, 2023). "Elevated glycolysis in cancer cells frequently results in accumulation of methylglyoxal, which is further metabolized to S-lactoylglutathione by glyoxalase 1 (GLO1) and subsequently to lactate in the reaction catalyzed by glyoxalase 2 (GLO2)." (PMID 34921655, 2022). "In 2010, our team, working with Mike Stratton and colleagues of the UK Cancer Genome, reported on copy number increase of GLO1 in human tumors—a mechanism of increased Glo1 expression in some tumors." (PMID 35269594, 2022). "In fact, since overexpression is present in various cancers, aberrant expression of Glo1 is involved in drug resistance." (PMID 35898868, 2022). "Cell permeable Glo1 inhibitor prodrugs have been developed to induce severe dicarbonyl stress as a prospective treatment for cancer—particularly for high Glo1 expressing-related multidrug-resistant tumors." (PMID 35269594, 2022). "It has been shown that elevated levels of MGO in the TME lead to the overexpression of an MGO detoxifier, glyoxalase I (Glo1), in cancer cells." (PMID 35936744, 2022). "In this case, it is necessary to explore the role of GLO1 and its inducers—trans-resveratrol-hesperetin (tRESHESP) in the clinical chemoprevention effect of cancers." (PMID 36612084, 2022). "OIP5-AS1 and miR-216a-5p/GLO1 form a competitive endogenous RNA (ceRNA) regulatory network in BC, thus promoting the malignant behavior of cancer cells." (PMID 36299824, 2022). "It plays a critical role in the development of innate and acquired drug resistance, and in cancer, overexpression of the GLO1 gene and protein is characteristic of cells with high glycolytic rates." (PMID 35992817, 2022). "In fact, knockdown of GLO1 can reduce the migration, invasion, colony formation, tubule formation, proliferation, and cell viability of carcinoma cells in breast cancer." (PMID 36612084, 2022). "The role of MG and Glo1 seems to be dependent on cancer type, since cancer tissues and cell lines of different molecular background and MG detoxication rate react differently under stress caused by MG." (PMID 34575195, 2021). "As a result of these unfavorable impacts, cancer cells depend on the outflow of aldehyde barrier proteins, for example, GLO1 to evade extreme aldehyde stress and FN3K to confine AGE-amassing." (PMID 35223406, 2021). "We investigated the role of MG and Glo1 in cancer chemotherapy related in multidrug resistance (MDR)." (PMID 34790575, 2021). "The pro-tumorigenic role, initially attributed to Glo1, has been further validated in the last decade by studies sustaining its role as potential target in cancer therapies." (PMID 33869040, 2021).
cancer (continued). "Glo1 expression data of 1,040 human tumor cell lines and 7,489 tumors were examined for functional correlates and impact of cancer patient survival." (PMID 34790575, 2021). "Given the association between Glo1 overexpression and the MDR in cancer chemotherapy, and the presence of Glo1 amplification in several human tumors, an anticancer strategy is further represented by the use of Glo1 inhibitory drugs." (PMID 33869040, 2021). "Following Glo1 inhibition, cancer cells switch from glycolysis to tricarboxylic acid (TCA) cycle to avoid apoptosis induced by MGO accumulation." (PMID 33869040, 2021). "One of the first developed GLO1-inhibiting agents in tumor cells was S-p-bromobenzylglutathione cyclopentyl diester that leads to apoptosis in GLO1-overexpressing cancer cells." (PMID 34440621, 2021). "Glo1, is overexpressed in advanced mPCa, where, through specific MG-derived AGEs, it acts as a determinant of cancer survival and metastatic behavior." (PMID 34199263, 2021). "Given the striking phenotypic effects observed by us in malignant cells with genetic GLO1 deletion, our ongoing investigations explore the function and therapeutic potential of GLO1 as a novel molecular cancer target." (PMID 32466621, 2020). "Further, a role of GLO1 in cancer cell chemoresistance has been demonstrated, and the development of pharmacological and genetic strategies modulating GLO1 for experimental cancer therapy has attracted significant attention." (PMID 32466621, 2020). "Because of this, an urgent need for the development of GLO1 inhibitor drugs for clinical cancer therapy is noted." (PMID 32721999, 2020). "Immature, proliferating tissues, as well as cancer cells, display a relatively high GLO1 and low GLO2 activity, whereas differentiated, mature tissues, in which cell anabolism and proliferation are reduced, show lower GLO1 and higher GLO2 activities." (PMID 33379155, 2020). "Overexpression of Glo1 in many cancer cells acts as an adaptive response to high glycolytic activity and elevated MGO, which is often associated with cancer cell survival and resistance to chemotherapeutic agents." (PMID 33396745, 2020). "For example, H3K4me3 in Glo1 gene that is overexpressed in many cancers has increased, whereas in Dynlt1a has both decreased and increased occupancies in treated ovary." (PMID 31084621, 2019). "The migratory ability of GLO1-depleted cancer cells increased up to 2.5-fold compared with control cells." (PMID 30674353, 2019). "The ability of Glo1-deleted cells to proliferate as allografts was impaired compared to parental NSCLC cancer lines." (PMID 31811141, 2019). "We validated this specific modulation of collagen gene expression in cancer cells upon GLO1 depletion at both mRNA and protein levels." (PMID 30674353, 2019). "Several studies depicted GLO1 as an amplified and/or overexpressed oncogene associated with a poor prognosis in various types of malignant tumors, thus considering the inhibition of GLO1 activity as a potential anti-cancer therapy." (PMID 30674353, 2019). "The results showed that the expressions of Glo1 in most cancer tissues were significantly higher than those in normal tissues." (PMID 31822263, 2019). "In order to know if there was a correlation between Glo1 and cancer, first, we compared the levels of expression between normal samples and patients with different kinds of cancers and presented them in a box plot." (PMID 31822263, 2019). "Glo1 represents an important mechanism for methylglyoxal detoxification, and has been shown to be elevated in a diverse set of cancer contexts." (PMID 31811141, 2019). "GLO1 inhibition in cancer cells leads to the accumulation of intracellular MG and induction of apoptosis." (PMID 30559934, 2018). "TLSC702 also enhanced caspase-3/7 activity in MDA-MB 157 cells, which is consistent with earlier studies in which GLO1 inhibition induced apoptosis in cancer cells." (PMID 30559934, 2018).
cancer (continued). "GLO1 has been reported to be amplified at the DNA, RNA, or protein level in a variety of primary human cancers and derived cell lines." (PMID 29385725, 2018). "To assess the role of GLO1 in ALDH1high basal-like cancer cells in detail, we used two kinds of short interfering RNAs (siRNAs) to silence GLO1 mRNA." (PMID 30559934, 2018). "The role of Glo1 in PCa carcinogenesis has supported the view of Glo1 both as a marker for diagnosis of PCa and a potential target for the development of novel anti-cancer or chemotherapeutic agents for PCa, which were indeed confirmed by some studies." (PMID 29385039, 2018). "This suggests it will be important to investigate the roles of GLO1 in ALDH1-positive CSCs in these cancers as well." (PMID 30559934, 2018). "Glo1 expression was higher in the cancer tissues than normal tissues (Mann-Whitney U test, p < 0.001)." (PMID 30559934, 2018). "GLO1 overexpression is evident in many cancer types, with increases typically ≤2-fold relative to normal tissue." (PMID 29385725, 2018). "The concept of increasing the local concentration of MG by targeting GLO1 in glycolytic tumors was initially proposed as a potential cancer treatment by Vince and co-workers." (PMID 29385725, 2018). "We report for the first time that glycolytic cancer cells present a specific response to MG challenge notably consisting of de novo expression of GLO1 and Nrf2 at both mRNA and protein levels." (PMID 28916747, 2017). "Our data demonstrate that cancer cells responded to both endogenous and exogenous MG stimulus by increasing their D-lactate secretion, an indicator of GLO1 detoxification." (PMID 28916747, 2017). "Cancer cell lines have an overexpression of glo-1 and MG, due to cellular response to cancer cell adaptation." (PMID 28698611, 2017). "GLO1 amplification and overexpression have been correlated with cancer progression and drug resistance." (PMID 28117708, 2017). "For example, several studies have reported that cultured cancer cells presenting with GLO1 gene amplification are more sensitive to GLO1 inhibition, in terms of growth inhibition and/or apoptosis induction, than cancer cells with normal GLO1 gene copy number." (PMID 28117708, 2017). "In summary, the ambivalent role demonstrated for GLO1 as a tumor promoter or suppressor is likely to be cancer type-dependent and it is expectable that cell lines with dissimilar backgrounds and MG detoxification rates will respond differently to MG stress." (PMID 28117708, 2017). "In this study, we demonstrate for the first time that glycolytic cancer cells are able to induce Nrf2 and GLO1 expression upon MG stress." (PMID 28916747, 2017). "High GLO1 expression and activity levels have been described in many types of cancer including colon, prostate, lung, melanoma and breast." (PMID 28117708, 2017). "In fact, Nrf2 and GLO1 favour the survival of cancer cells by protecting them from excessive dicarbonyl and/or oxidative stress, both of which have been implicated in cancer initiation and progression." (PMID 28916747, 2017). "GLO1 appears to be a dual mediator for growth regulation in cancer as it has been described both as an oncogene and a tumor suppressor." (PMID 27759563, 2016). "There were 14 tumour suppressor genes found and currently Glo-1 is the only one for which a readily available strategy for increased cancer prevention exists – dietary Glo-1 inducers in functional foods." (PMID 27406712, 2016). "In fact, cancer cell lines with an amplification of the GLO1 gene were shown to have a higher sensitivity to the growth inhibitory effect of a potent GLO1 inhibitor." (PMID 27999356, 2016). "In order to exclude the potential MG acute toxicity on cancer cells, we also measured Glo-1 activity in MDA-MB-231 and MCF-7 cells after 3 weeks of chronic treatment at lower concentrations of MG (5-50 μM)." (PMID 24978626, 2014). "The basic biochemistry of GLO1 has been reviewed elsewhere, as have its roles in cancer and diabetic complications." (PMID 23181072, 2012).
cancer (continued). "Glo1 has received particular attention in the last decade as an anti-cancer target with many publications assuring its importance as an anti-cancer valid target." (PMID 23174893, 2012). "Recent studies have suggested a vital role of GLO1 in several cancer types in the removal of methylglyoxal (MG), which is considered carcinostatic, resulting in the development of GLO1 inhibitors as anti-tumor agents." (PMID 22479608, 2012). "Diagram illustrating the role of GLO-1 in cancer immunopathology." (PMID 40727469, 2025). "While such a combined approach might compromise GLO-1’s detoxification function the overall effect could ultimately be detrimental to cancer development." (PMID 40727469, 2025). "This suggests that MG scavengers and GLO1 agonists are not only indicated for cancer prevention but may also improve the sensitivity of chemotherapy, especially in high-risk groups with metabolic abnormalities." (PMID 40352588, 2025). "Glyoxalase 1 (Glo1) functions as a catalyst that neutralizes methylglyoxal (MG), a highly reactive glycating agent predominantly produced during glycolysis—a metabolic pathway upregulated in cancer cells." (PMID 41009024, 2025). "Therapies targeting GLO1 offer a novel strategy for cancer therapy." (PMID 40352588, 2025). "The role of GLO-1 in survival and disease course differs depending on the specific cancer." (PMID 40727469, 2025). "However, it is worth mentioning that inhibition of glyoxylase 1 (GLO1) in cancers can increase levels of DNA-AGE and RAGE that is cytotoxic to glioma cells, implying the dialectical roles of CEdG in cancers." (PMID 40959494, 2025). "The growing body of evidence indicates that dysregulation of GLO-1 expression and activity may be a key factor in cancer initiation, progression, and the development of therapeutic resistance." (PMID 40727469, 2025). "In this context, our results are consistent with these findings, suggesting that ACh-induced Glo1 down-regulation and MG-H1 accumulation may promote cancer cell migration and invasion, as well as proliferation, by inducing a pro-tumorigenic environment." (PMID 40362346, 2025). "This context may also contribute to the variable (pleiotropic) expression of GLO-1 observed across different cancer types and stages." (PMID 40727469, 2025). "Besides, we utilized TISCH database and found that comparatively to other types of cells, GLO1 was mainly expressed in cancer cells." (PMID 40492378, 2025). "GLO1 overexpression endows cancer cells with stronger MG detoxification ability, prevents them from MG-induced apoptosis, and promotes tumor invasion and development of drug resistance (a discussion of the toxic killing effects of MG on cancer cells can be found in Section 4)." (PMID 40352588, 2025). "Pan-cancer analysis of GLO-1 expression was performed using the SangerBox and TIMER2.0 databases." (PMID 40727469, 2025). "As a result, the present study provides a systematic evaluation of the GLO-1 gene’s role in cancer progression and development, encompassing an analysis of the impact of genetic modifications and mutations on GLO-1, as well as the protein’s immunotherapeutic function." (PMID 40727469, 2025). "At the same time, GLO1 inhibitors, such as S-p-bromobenzylglutathione cyclopentyl diester, are being investigated as chemotherapy adjuncts to target the highly metabolically active GLO1-expressing cancer cells." (PMID 41100182, 2025). "It has been emphasized that this ambivalent role of Glo-1 as a tumor promotor or suppressor might be cancer-type dependent." (PMID 39682111, 2024). "Cancer cells may exhibit survival mechanisms to counter high MG levels, such as increased Glo1 expression and activity." (PMID 38398772, 2024). "Importantly, to date, there are fewer studies on Glo2 than on Glo1, which, instead, consistently show overexpression of Glo1 in different cancer cell lines." (PMID 39456676, 2024).
cancer (continued). "We then performed a gene set enrichment analysis (GSEA) searching for statistical associations between the observed enhancer/promoter methylation alterations to genes under GLO1-depletion condition and those contained in a collection of pathways related to cancer development and progression." (PMID 36998085, 2023). "Then, we sought to explore whether MG stress could up regulate DNMT3B level in other human cancer cell types that we stably depleted for GLO1 expression." (PMID 36998085, 2023). "The mechanism of GLO1 amplification in cancer is unknown but a suggestion came from a study of GLO1 duplication in mouse embryonic stem cells." (PMID 35269594, 2022). "Additionally, GLO1 is the main amplified gene of locus 6p21.2 in human cancers, providing a potential target for therapy in cancers with GLO1 amplification." (PMID 36612084, 2022). "These authors indicated that GLO1 inhibits apoptosis of cancer cells by inactivating caspases treated with anticancer drugs, while noting that this may be a reversible effect." (PMID 35992817, 2022). "GLO1 expression reportedly is upregulated in several malignant tumors." (PMID 35143416, 2022). "Interestingly, overexpression of Glo1 in some cancer cells (including ATC) allows utilization of the activity of this enzyme in anti-cancer treatment." (PMID 34575195, 2021). "Conversely, Glo1 is a common mediator of MDR in cancer chemotherapy." (PMID 34790575, 2021). "From the studies herein, dysregulation of Glo1 in tumor hypoxia may contribute to MDR in cancer chemotherapy and increased tumor survival." (PMID 34790575, 2021). "Adjunct chemotherapy with Glo1 inhibitor may improve treatment outcomes in clinical cancer chemotherapy, particularly where high expression of Glo1 is a risk predictor of poor survival outcome." (PMID 34790575, 2021). "It has been validated that Glo-1 expression and activity are connected with cancer growth movement." (PMID 35223406, 2021). "Thus, the correct balance between Glo1 activity and the increased MGO production, associated to the high glycolytic flux in cancer cells, is likely crucial for tumor growth response." (PMID 33869040, 2021). "Thus, the production of toxic MGO is increased in cancer cells, and as a form of defence, increased GLO1 expression and glyoxalase system optimization would be noted among the mutagenic aspects that cancer cells suffer." (PMID 32721999, 2020). "An additional ramification of the current results may be in the area of cancer biology, where there has been interest in the potential use of GLO-1 inhibitors to target metabolic vulnerabilities of cancer cells." (PMID 32795389, 2020). "In cancer cells, Glo1 inhibitors are considered potential anticancer targets." (PMID 33396745, 2020). "The role of GLO1 in cancer progression remains controversial." (PMID 30674353, 2019). "The cancer-specific role of Glo1 suggests the need of further studies on a case-by-case basis." (PMID 31174324, 2019). "We then conducted a survival analysis of the Glo1 gene in cancers." (PMID 31822263, 2019). "It is unclear whether PFSE and its stilbene derivatives inhibit cancer cell proliferation via human glyoxalase I (GLO I), the rate-limiting enzyme for detoxification of methylglyoxal." (PMID 31517069, 2019). "In good accordance with this hypothesis, GLO1-depleted cancer cells show augmented ECM reorganization, anchorage-independent growth and increased migration/invasion ability; all inhibited in the presence of MG scavengers." (PMID 30674353, 2019). "TLSC702, a specific GLO1 inhibitor, induces MG accumulation and apoptosis in cancer cells." (PMID 30559934, 2018). "Cancers that exhibit the Warburg effect may elevate expression of glyoxylase 1 (GLO1) to detoxify the toxic glycolytic byproduct methylglyoxal (MG) and inhibit the formation of pro-apoptotic advanced glycation endproducts (AGEs)." (PMID 29385725, 2018).